RN7SL290P (RNA, 7SL, cytoplasmic 290, pseudogene)
Gene: Miscellaneous RNA gene on chromosome 1 (51,995,740 to 51,996,039, forward strand). Ensembl gene ENSG00000264613.
Homologues: Orthologues: chimpanzee Metazoa_SRP (99% identical), macaque Metazoa_SRP (89% identical). Paralogues in human: RN7SL1 (83% identical), RN7SL2 (83% identical), RN7SL3 (83% identical), RN7SL220P (80% identical), RN7SL126P (79% identical), RN7SL333P (79% identical), RN7SL664P (79% identical), RN7SL45P (79% identical), RN7SL743P (79% identical), RN7SL769P (79% identical), RN7SL7P (78% identical), RN7SL828P (78% identical), and 702 more.